TNF (tumor necrosis factor)
Diseases named in the same sentence as TNF in open-access papers (continued):
Sharing a sentence is not in itself a finding about the gene and the disease.
infection (continued). "We then investigated CAP status using the standard whole blood TNF response assay at multiple timepoints (i.e., 4-, 16-, and 48-hours) following infection." (PMID 35784337, 2022). "Biological disease modifying antirheumatic drug (bDMARDs), such as anti-TNF-a monoclonal antibodies, recombinant IL-1receptor-targeted antagonist and IL-23 antagonist have been used, but there are increased risks of infection." (PMID 35365205, 2022). "The unstimulated cytokine concentrations post-infection were within the reference range, and the concentrations of TNF-α and IL-6 were significantly lower post-infection than during antibiotic therapy." (PMID 35360000, 2022). "TNF-α is essential for stimulating the chemotaxis of inflammatory cells to sites of infection and leads to granulomatous response to containment disease progression." (PMID 35177742, 2022). "The results manifest that the mRNA levels of pro-inflammatory cytokines (IL-1β, IL-6, and TNF-α) in the PBS group increased significantly after infection." (PMID 35123452, 2022). "In these mice, strain Hoti infection produced lower TNF-α responses compared to Afg09-2990 on day 4 post-infection as determined by ELISA." (PMID 35587473, 2022). "Apoptosis genes such as caspase-3 and 9, TNF-α and pyroptosis-related genes caspase-1, IL-18 and IL-1β mRNAs showed increased expression during infection." (PMID 36298749, 2022). "Eighteen studies involving 37,693 patients with RA, PsA, or AS evaluated anti-TNFα drugs and reported a significant increase in serious infections." (PMID 34790122, 2021). "In a murine model of influenza A viral (IAV) infection Ifnlr1 mRNA expression on DCs increased following infection, which correlated with increased IFNγ and tumor necrosis factor (TNF) production by lung CD8+ T cells." (PMID 34899712, 2021). "Increases in IL-15, IL-1β, IL-6, and TNF-α levels were slightly more delayed in the CSF, beginning closer to day 6 post-infection." (PMID 34001896, 2021). "The general state of tissue inflammation has come to be recognised as the result of Th17 cells producing IL-17, IL-6, IL-22, and TNF-α to activate several cell linages to recruit effector cells like neutrophils to the site of infection." (PMID 33546104, 2021). "The main reason is associated with infection of SARS-CoV-2 elicitation a high production of cytokines including IL-1, TNF-α and IFN, which lead to down-regulate CYP3A4 and decrease elimination rate of LPV/RTV." (PMID 34899329, 2021). "When microglia are stimulated by infection, trauma and other harmful stimuli, they will activate them into M1 phenotype and release TNF-α, IL-6 and IL-12, among which TNF-α is one of the markers of M1 phenotype microglia." (PMID 34135761, 2021). "On the basis of a literature review, it appears that only TNF has been investigated in VSV pathogenesis, showing more rapid induction of TNF by an attenuated VSV mutant after infection but more drastic TNF induction later in infection by wild-type VSV in mice." (PMID 34578166, 2021). "More importantly, we found that such TNFα-mediated enhancement during infection was 2- to 3-folds reduced in Mincle-/- MΦs (Il27, Cxcl10, Ccl2), implying the mitigation of proinflammatory responses." (PMID 34320039, 2021). "IL-1β induces other cytokines including IL-1β itself, IL-1RA, TNFα, IL-6, and chemokines and adhesion molecules to promote early recruitment of neutrophils and other immune cells to infection sites." (PMID 33571211, 2021). "Liver samples were collected approximately 7 d prior to infection and then on day 10 post-infection and evaluated for gene expression of the inflammatory cytokines IL-6 and TNF-α, and the acute-phase protein haptoglobin." (PMID 34673945, 2021). "IL-22 can act synergistically with TNFα in response to infection-promoting chemokine expression (including CXCL9, CXCL10 and CCL5) by human keratinocytes." (PMID 34207946, 2021).
infection (continued). "Compared with WT, the T12D mutant had a significant increase in the expression of TNF-α at various time points, starting from 12 h after infection, whereas the IL-1β expression was slightly improved as compared to that of the WT." (PMID 33868202, 2021). "Independent of the role of hepcidin, several other cytokines such as tumor necrosis factor alpha, interferon gamma, interleukin-1, and interleukin-6 also modulate iron metabolism and the iron-withholding defense during infection." (PMID 34247585, 2021). "Pro-inflammatory markers regulated by PARPs such as TNF-α and IL-6 have been observed to be upregulated during infection that contribute towards the cytokine storm during infection." (PMID 34485381, 2021). "IFN-γ also synergistically works with TNF-α (the fifth most common vaximmutor) to promote the Th1 response against pathogen infection." (PMID 33777032, 2021). "On the other hand, this inflammatory response was more efficiently regulated in the later stages of the infection, as evidenced by decreased levels of neutrophils, TNF-α, CCL2, and IL-6 and the increases in the regulatory cytokines IL-10 and IL-27." (PMID 34207076, 2021). "In a mouse model of limbic epilepsy, activation of TNF-α signaling leads to overexcitability and acute seizures following infection with Theiler’s murine encephalomyelitis virus (TMEV)." (PMID 34832914, 2021). "At 12 h post-infection, total cellular RNAs were extracted and the viral RNA accumulation as well as the mRNA levels of 5 inflammatory cytokines, such as IL-6, IL-1β, TNF-α, TGF-β and IL-10, were examined using qRT-PCR." (PMID 34335977, 2021). "Twelve hours after infection, the levels of circulating inflammatory cytokines (IL-1β, IL-6, IL-18, and TNF-α) were still hardly detectable in most of the animals." (PMID 34236052, 2021). "Patients hospitalized with severe influenza due to infection with avian H5N1 exhibit exacerbated levels of circulating pro-inflammatory cytokines including TNF-a, IL-6, and sIL-2r, IP-10, and MIG." (PMID 34959590, 2021). "Other in vitro and in vivo studies of infection in the presence of purified exosomes have demonstrated their immunomodulatory properties, leading to the impairment of TNF and IL-8 production and increased parasite load." (PMID 34711290, 2021). "The direct antiviral activity of TNF during mice infections was demonstrated in another study using a recombinant VACV expressing mouse TNF." (PMID 34451529, 2021). "In animal models of infection, TNF, synergistically with interferon (IFN) γ, has been shown to interfere with the replication of diverse viruses, such as hepatitis B virus or murine cytomegalovirus, among others." (PMID 34451529, 2021). "KO of MyD88 showed an even greater reduction in both IL-6 and TNFα secretion from 3 to 48 h post infection." (PMID 34280250, 2021). "After 8 h of infection, we measured significantly higher TNF-α levels in the untreated CASP animals and also CASP animals treated with DFX." (PMID 33466819, 2021). "The consumption of propionate by AIEC pathobionts leads to an increase in TNF-α production by macrophages upon infection through the bacterial methyl-citrate pathway." (PMID 33769191, 2021). "Inhibition of FAK in THP-1 macrophages increased production of TNF-α and IL-1β upon infection with Mtb compared to control THP-1 macrophages, whereas FAK overexpression blocked the production of TNF-α and IL-1β." (PMID 34745115, 2021). "Additionally, IL-6 and TNF-α have been shown to be permeable to the blood-brain barrier, with potential interactions with the hypothalamus to induce subjective feelings of sickness and associated behaviors as a self-defense strategy during fevers in response to an infection." (PMID 33642989, 2021). "NF-κB is believed to be a major regulator of inflammation, and IL-1β, IL-6 and TNF-α are rapidly released in response to tissue injury or infection." (PMID 35096806, 2021).
infection (continued). "In the case of TB, TNF, a component of the early response, is known to be critical for infection control." (PMID 34755600, 2021). "After infection with Mtb, these mice exhibit increased levels of the pro-inflammatory cytokines TNF and IL-12 followed by an enhanced activation of CD4+ T cells in the lung, which eventually culminates in reduced bacterial burdens." (PMID 35116036, 2021). "On the other hand, as a result of infection, a significant increase of TNF-α was observed in infected and untreated rats with a concomitant reduction of the anti-inflammatory IL-10." (PMID 34829722, 2021). "The production of IFN-γ and TNF-α during the acute phase of the infection was previously related to resistance to T. cruzi infection." (PMID 34869064, 2021). "To investigate the effector function of these cells in the chronic stage of infection, we then analyzed their production of TNF, IL-12 and iNOS." (PMID 33968021, 2021). "Inflammatory cytokines such as TNF-α have important roles in the pathophysiology of cerebral malaria based on murine models of infection." (PMID 33803419, 2021). "Higher mRNA levels of inflammatory cytokines IL-1β, IL-6, IL-8, and TNF-α were observed during early symptomatic infection (JM-1) compared to healthy controls." (PMID 34669281, 2021). "The mRNA level of IL-1β, IL-8, TNF-α, and IL-2 was down-regulated (<1-fold) in the early stages of infection." (PMID 34603235, 2021). "TLR4 allows translocation and activation of the transcription factor NF-ĸB, which stimulates synthesis and secretion of cytokines (IL-6, TNFα) at the site of the infection, which will propagate the immune response." (PMID 33801785, 2021). "Given the relevance of other pro-inflammatory cytokines in the immune response against N. caninum, we investigated here the role of TNF pathway in this infection." (PMID 35071042, 2021). "Inflammatory cytokine signals are released during reactions to infection, tissue injury, and stress by immune cells, such as TNF-α, IFN-γ, and IL-2." (PMID 34679061, 2021). "Peroxisome proliferator activator receptor gamma (PPARγ) is an important regulator of the macrophage pro-inflammatory responses to infection regulating TNFα and IL-6 production." (PMID 34054509, 2021). "SAA is an apolipoprotein, which appears in the bloodstream as the first response protein up to 24-48 h after the occurrence of an inflammatory factor, such as infection, and its secretion is dependent on IL-1 and/or TNF-α." (PMID 34316205, 2021). "We found a marked increase in the release of the pro-inflammatory cytokines TNF-α, IL-1β, and IL-6, after infection, when compared to controls." (PMID 33669494, 2021). "Infection of HSV-2 caused a significant reduction in HeLa cells and increased the gene expression of inflammatory cytokines TNFα, IL6, IL8 and IP10." (PMID 34943765, 2021). "The inflammatory response following severe injury or infection is known to be regulated by a complex network of cytokines, initiated by tumor necrosis factor alpha (TNF-alpha)." (PMID 31932967, 2021). "Initially, we observed that mice deficient in TNFα were much more susceptible to intranasal infection with Cp1038 when compared to wild-type (WT) B6 mice, highlighting a critical role for TNFα in the murine infection model." (PMID 35174101, 2021). "The present work expanded on these observations by demonstrating that infection with a DL isolate induced comparatively higher TNF, CXCL9 and CXCL10 expression than CL in cultured monocytes obtained from both CL and DL patients." (PMID 34568099, 2021). "While there were still no off-target effects as evidenced by testing responses to flagellin, both inhibitors decreased IL-6 and TNFα levels in response to infection and control agonists." (PMID 34280250, 2021). "As shown in a range of studies, the simultaneous expression of the cytokines IFN-γ, TNF, and IL-2 enables T cells to a more effective immune response towards different infections in mice and men." (PMID 34351501, 2021).
infection (continued). "The results showed that the ability of MS_Rv2650c to stimulate the secretion of cytokines TNF-α, IL-1β, IL-6, and IL-10 was lower than that of MS_Vec after 24 h of infection (paired t-test; P = 0.000006, P = 0.004, P = 0.01, P = 0.00002, respectively)." (PMID 35111145, 2021). "Infection with T. gondii alone caused little LDH release in each BMDM genetic background, but stimulation with TNF and Z-VAD-FMK (a pan-caspase inhibitor that drives necroptosis) caused a similar increase in LDH release in WT and ZBP1−/− BMDM." (PMID 33526566, 2021). "Levels of IFN-γ, TNF-α, and IL-1β were significantly reduced after 7 days of infection in the cultures treated with decitabine, but the quantification of IL-10 remained unchanged, suggesting an increase in anti-inflammatory ratio and control of inflammation." (PMID 33921194, 2021). "It was interesting to note the upregulation of inflammatory cytokines IL-15 and TNFα in response to PBMC infection with SPPV." (PMID 34211465, 2021). "In the serum, only IL-10 and IL-13 were significantly increased, while in urine IFN-γ, TNF-α, IL-13, IL-1β, IL-22, and IL-10 were significantly increased in by infection." (PMID 34662329, 2021). "IFN-γ is secreted by innate immune cells soon after infection and stimulates DC, upregulating proinflammatory factors such as IL-12, IL-27, and TNF-α." (PMID 34093711, 2021). "TNF-α is a major pro-inflammatory cytokine released from the intestinal epithelium in response to infections with diarrheal pathogens like Vibrio cholerae, Salmonella enterica, and C. jejuni." (PMID 33669494, 2021). "While some differences exist, many features of the immune response to infection with Ft are shared between the two mouse strains, including the protective roles of IFNγ, TNFα, and α/β T cells." (PMID 33946283, 2021). "An increase in TNF-α serum concentration has been also observed in the early phase of infection by Lena strain as well as by other virulent PRRSV strains." (PMID 34046040, 2021). "Treatment with DHEA has been reported to enhance thymocyte proliferation and reduce TNF-α production during the acute phase of infection." (PMID 34113341, 2021). "These essential properties of TNF-α to limit local inflammation can have disastrous consequences once an infection becomes systemic or LPS enters the blood in larger quantities." (PMID 34205208, 2021). "On day 3, the CA09 + H3N2-M2 induced significantly higher levels of TNF-α than the other two infection groups." (PMID 34960604, 2021). "TNF-α, a member of the pro-inflammatory cytokine family, stimulated the recruitment of neutrophils and monocytes to the site of infection and promoted a sustained response to inflammation in the TME." (PMID 33460401, 2021). "Another previous study showed that the consequences of early life stress-induced infection altered cytokine production, such as IL-6, TNF-α, or IL-1β, and changed behaviors in later life." (PMID 33441182, 2021). "Protein concentrations increased post-infection in both groups with a peak expression at 168 hpi, except for TNFα and IL-8 which demonstrated a sharp increase at 24 hpi." (PMID 34740333, 2021). "Specifically, we identified a unique population of CD4+/CD8+ double positive T cells (DP T cells) that upregulated inflammatory cytokines such as TNF-⍺ as well as Granzyme B over the course of infection." (PMID 34929014, 2021). "In the same study, intravenous infection with hvKP significantly decreased the blood TNF-α level in diabetes mellitus mice, whereas the IL-1β level tended to increase in the blood of both infected nondiabetic and diabetic groups." (PMID 34204632, 2021). "The low dose infection group maintained a consistent increase in the CD8+TNF-α+T cells at 1- and 3-weeks post-infection compared to the pre-infection levels." (PMID 34484203, 2021). "In the lung, the TNF-α mRNA expression in group IV was lower (p < 0.05) compared with expression level in group I at day 1 post-infection." (PMID 34988139, 2021).
infection (continued). "A significant body of research also indicates that type I interferon, TNF-α, B-cell released antibodies, and other cytokines play a significant role in the viral immune response that combats infection against viral pathogens and promotes clearance." (PMID 34882690, 2021). "Impaired ATG16L1, IRGM or NOD2 expression in macrophages increases intracellular AIEC with enhanced secretion of IL-6 and TNF in response to infection." (PMID 33468624, 2021). "For having remained below the technique detection limit, we did not interpret the following values: uninfected mice, IL-2, IL-4, IL-10, and IL-17 values of infected mice, as well as IFN-γ, TNF-α, and IL-6 levels at the infection times from 6 to 240 h." (PMID 34660334, 2021). "At 24 h post-infection, TNF, IL-17 and NF-kB pathways scored relatively high Odds-Ratios compared to other gene sets." (PMID 34970230, 2021). "This anti-inflammatory role of TNF has also been described in murine models of infection including Corynebacterium parvum or M. bovis BCG." (PMID 34093562, 2021). "Our findings in human infection largely concur with earlier findings in the mouse model, specifically chronically elevated IL-13 and TNFα in the bladder tissue of egg-injected mice and only transient changes in IL-17." (PMID 34662329, 2021). "We also examined if a shorter treatment with the anti-TNFα antibodies after infection had a diminished effect on the disease progression." (PMID 35174101, 2021). "(2017) discovered that TNF- levels were significantly higher in the livers of BALB/c mice upon infection with B. pseudomallei, while levels were lesser in the liver of C57Bl/6 mice." (PMID 34456925, 2021). "At that time, H9N2 AIV infection increased TNF-α expression by 6.5 fold, and DATS treatment reduced it to 3.9 fold." (PMID 34412671, 2021). "During infection, vMIA/vIBO suppress an early involvement of TNF beyond BAX/BAK such that the double-mutant virus drives TNFR1-dependent death by 24 hpi." (PMID 34578288, 2021). "Several independent studies report secretion of TNF peaking at 100–500 pg/mL serum 4–5 days after infection of pigs with CSFV." (PMID 34696447, 2021). "Significant differences were only noted in IFN-γ and TNF-α responses between infection groups at week-7." (PMID 34314415, 2021). "The cytokine levels in natural course of infection have been investigated in a number of studied and IL-6, IL-10, TNF-α and IFN-γ were found to be major cytokines during the natural course of infection." (PMID 34851958, 2021). "In the inflammatory phase, keratinocytes, fibroblasts, and leukocytes produce inflammatory cytokines, such as interleukin (IL)-1β, IL-6, and tumor necrosis factor (TNF)-α, which are important for leukocyte recruitment and protection against infection." (PMID 34829749, 2021). "The results showed that most inflammatory factors, including IL-1β, IL-6, IL-8, and TNF-α, were significantly increased after infection." (PMID 34593766, 2021). "Surprisingly, infection with the Δrgg3 mutant led to approximately 4-fold decreased NF-κB reporter activity and 20-fold decreased TNF-α and 25-fold decreased IL-6 production compared to infection with WT or Δrgg2 strain." (PMID 33947757, 2021). "The expression level of S100B proteins increases in response to factors upregulated during infections such as TNFα, IL-1β, IL-6, and IL-8, also reported to be increased in prenatal infection models." (PMID 34741005, 2021). "Corroborating its anti-inflammatory action, Quercetin treatment significantly reduced TNF and IL-6 production in human macrophages following infection with P. gingivalis and F. nucleatum." (PMID 34899728, 2021). "S.pn infection led to significantly increased inflammatory cytokine levels of TNF-α, IL-1β, and IL-6 in BALF (p < 0.01), while QFY treatment of infected mice led to significantly decreased BALF levels of these cytokines." (PMID 34950611, 2021).